IGLV1-40 (immunoglobulin lambda variable 1-40)
Description:
V region of the variable domain of immunoglobulin light chains that participates in the antigen recognition. Immunoglobulins, also known as antibodies, are membrane-bound or secreted glycoproteins produced by B lymphocytes. In the recognition phase of humoral immunity, the membrane-bound immunoglobulins serve as receptors which, upon binding of a specific antigen, trigger the clonal expansion and differentiation of B lymphocytes into immunoglobulins-secreting plasma cells. Secreted immunoglobulins mediate the effector phase of humoral immunity, which results in the elimination of bound antigens. The antigen binding site is formed by the variable domain of one heavy chain, together with that of its associated light chain. Thus, each immunoglobulin has two antigen binding sites with remarkable affinity for a particular antigen. The variable domains are assembled by a process called V-(D)-J rearrangement and can then be subjected to somatic hypermutations which, after exposure to antigen and selection, allow affinity maturation for a particular antigen.
Synonyms: IGLV140; V1-13
Tractability: Antibody: its Gene Ontology location is reachable by antibodies, with high confidence; UniProt places it where antibodies can reach, with medium confidence; UniProt predicts a signal peptide or a membrane-spanning region.
Gene: Immunoglobulin variable (V) gene on chromosome 22 (22,409,766 to 22,410,282, forward strand). Ensembl gene ENSG00000211653.
Subcellular location: Secreted; Cell membrane
Pathways (Reactome):
Immune System: Antigen activates B Cell Receptor (BCR) leading to generation of second messengers; CD22 mediated BCR regulation; Classical antibody-mediated complement activation; FCERI mediated Ca+2 mobilization; FCERI mediated MAPK activation; FCERI mediated NF-kB activation; FCGR activation; Fc epsilon receptor (FCERI) signaling; Immunoregulatory interactions between a Lymphoid and a non-Lymphoid cell; Initial triggering of complement; Regulation of Complement cascade; Regulation of actin dynamics for phagocytic cup formation; Role of LAT2/NTAL/LAB on calcium mobilization; Role of phospholipids in phagocytosis
Disease: FCGR3A-mediated IL10 synthesis; FCGR3A-mediated phagocytosis; Potential therapeutics for SARS
Hemostasis: Cell surface interactions at the vascular wall
Vesicle-mediated transport: Scavenging of heme from plasma
Gene Ontology:
Molecular function: antigen binding
Biological process: immune response
Cellular component: extracellular region; immunoglobulin complex; plasma membrane
Homologues: Paralogues in human: IGLV1-50 (86% identical), IGLV1-44 (81% identical), IGLV1-47 (81% identical), IGLV1-51 (80% identical), IGLV1-36 (77% identical), IGLV2-18 (75% identical), IGLV2-11 (73% identical), IGLV2-14 (73% identical), IGLV2-8 (73% identical), IGLV2-23 (69% identical), IGLV6-57 (69% identical), IGLV2-33 (64% identical), and 81 more.
Diseases named in the same sentence as IGLV1-40 in open-access papers:
IGLV1-40 is named in the same sentence as 1 disease in open-access papers, as found by Europe PMC text mining. Sharing a sentence is not in itself a finding about the gene and the disease. The quoted sentences say what the papers report.
COVID-19 (1 paper, 2021). A disease caused by infection with severe acute respiratory syndrome coronavirus 2. "Moreover, we found that the IGLV1-40_P01703 (Immunoglobulin lambda variable 1-40) was significantly and negatively associated with clinical indicators of systemic inflammation (Monocytes and globin) in recovered COVID-19 patients." (PMID 34035220, 2021).